NOTCH2NLC (notch 2 N-terminal like C)
Description:
Human-specific protein that promotes neural progenitor proliferation and evolutionary expansion of the brain neocortex by regulating the Notch signaling pathway. Able to promote neural progenitor self-renewal, possibly by down-regulating neuronal differentiation genes, thereby delaying the differentiation of neuronal progenitors and leading to an overall final increase in neuronal production. Acts by enhancing the Notch signaling pathway via two different mechanisms that probably work in parallel to reach the same effect. Enhances Notch signaling pathway in a non-cell-autonomous manner via direct interaction with NOTCH2. Also promotes Notch signaling pathway in a cell-autonomous manner through inhibition of cis DLL1-NOTCH2 interactions, which promotes neuronal differentiation (By similarity).
Synonyms: ETM6; NIID; OPDM3
Tractability: Antibody: UniProt places it where antibodies can reach, with high confidence; its Gene Ontology location is reachable by antibodies, with high confidence.
Gene: Protein-coding gene on chromosome 1 (149,390,621 to 149,471,833, forward strand). Ensembl gene ENSG00000286219.
Subcellular location: Secreted
Pathways (Reactome):
Signal Transduction: Expression of NOTCH2NL genes; NOTCH2 Activation and Transmission of Signal to the Nucleus
Gene Ontology:
Molecular function: protein binding; calcium ion binding
Biological process: cerebral cortex development; positive regulation of Notch signaling pathway
Cellular component: extracellular region
Genetic constraint (gnomAD): Loss-of-function variants: 2 observed, 1.49 expected, observed/expected ratio (o/e) 1.34, 90% interval 0.44 to 1.92. That is too few expected variants to judge how well the gene tolerates losing a copy. Missense variants: 34 observed, 31.85 expected, observed/expected ratio (o/e) 1.07, 90% interval 0.81 to 1.42. Synonymous variants: 15 observed, 11.39 expected, observed/expected ratio (o/e) 1.32, 90% interval 0.87 to 1.86.
Homologues: Orthologues: Drosophila melanogaster N (37% identical), Caenorhabditis elegans lin-12 (6% identical), zebrafish notchl (1% identical). Paralogues in human: NOTCH2NLB (85% identical), NOTCH2 (81% identical), NOTCH2NLA (81% identical), NOTCH2NLR (78% identical), NOTCH1 (39% identical), NOTCH3 (33% identical), SNED1 (11% identical).
Diseases named in the same sentence as NOTCH2NLC in open-access papers:
NOTCH2NLC is named in the same sentence as 12 diseases in open-access papers, as found by Europe PMC text mining. Sharing a sentence is not in itself a finding about the gene and the disease. The quoted sentences say what the papers report.
neuronal intranuclear inclusion disease (9 papers, 2021 to 2025). Neuronal intranuclear inclusion disease (NIID) is a very rare multisystem neurodegenerative disorder characterized by the presence of eosinophilic intranuclear inclusions in neuronal and glial cells, and neuronal loss. "Another gene with pathogenic REs, NOTCH2NLC, was recently identified in Japanese patients with sporadic neuronal intranuclear inclusion disease." (PMID 39425080, 2024). "Of interest, NOTCH2NLC has also been previously identified as the same gene causing neuronal intranuclear inclusion disease (NIID), a condition characterized by peripheral neuropathy and cognitive impairment, phenotypically unrelated to ET." (PMID 35401394, 2022). "Neuronal Intranuclear Inclusion Disease (NIID) is a neurodegenerative disease caused by an aberrant amplification of the GGC repeat sequence in the 5′untranslated region (5′UTR) of the NOTCH2NLC (Notch 2 N-Terminal Like C) gene." (PMID 41154122, 2025).
oculopharyngodistal myopathy (2 papers, 2022). Oculopharyngodistal myopathy (OPDM) is a rare, adult-onset hereditary muscle disease. "Intranuclear inclusions are also observed in NIID, which is a neurological disease caused by GGC repeat expansion of the NOTCH2NLC gene, which has also been reported to be associated with oculopharyngodistal myopathy with intranuclear inclusions." (PMID 35942699, 2022).
Leukoencephalopathy (1 paper, 2023). This term describes abnormality of the white matter of the cerebrum resulting from damage to the myelin sheaths of nerve cells. "Two studies revealed CGG repeat expansions in NOTCH2NLC also cause OPDM phenotype (named OPDM3); about half of patients with OPDM phenotype with the NOTCH2NLC expansions (OPDM3) show leukoencephalopathy, neuropathy, or other signs compatible with NIID1." (PMID 36670296, 2023).
NOTCH2NLC also shares sentences with these, for which no sentence is quoted: amyotrophic lateral sclerosis (1 paper); Huntington disease-like 2 (1); myotonic dystrophy type 1 (1); neurological disease (1); neuropathy (1); Parkinsonism (1); spinocerebellar ataxia (1); spinocerebellar ataxia type 31 (1); spinocerebellar ataxia type 36 (1).